IL6 (interleukin 6)
Diseases named in the same sentence as IL6 in open-access papers (continued):
Sharing a sentence is not in itself a finding about the gene and the disease.
psoriasis (continued). "Materials and Methods: This review synthesizes the current evidence on key salivary cytokines—IL-1β, IL-6, TNF-α, and IL-17—in relation to psoriasis pathogenesis, diagnosis, and treatment monitoring." (PMID 40731810, 2025). "In fact, studies have shown that patients with psoriasis tend to have higher serum levels of TNF-α, IL-6, and resistin." (PMID 40740781, 2025). "In psoriasis, the IL-17/IL-23 axis, TNF-α, and interleukin-6 (IL-6) are known to contribute to the development of MetS." (PMID 40870891, 2025). "Central cytokines driving the chronic inflammation characteristic of psoriasis include IL-17, IL-22, TNF-α, and IL-6." (PMID 40428224, 2025). "Psoriasis, as an inflammatory, immune disease, significantly elevates the levels of inflammatory factors and cytokines, such as TNF-α and IL-6." (PMID 41465997, 2025). "This hormone further regulates immune cells and cutaneous cells, promoting the release of core pro-inflammatory cytokines such as IL-6, IL-17, and TNF-α, ultimately exacerbating the severity of psoriatic lesions and prolonging the chronicity of psoriasis." (PMID 41357183, 2025). "However, IL-6 is not a specific marker for psoriasis as its aberrant expression may be associated with other diseases." (PMID 40898481, 2025). "Inflammatory cytokines, mainly IL-6 and TNF-α, are involved in the inflammatory process of psoriasis." (PMID 40004904, 2025). "Martina Morelli also found that IL-6 and TNF-α are aberrantly expressed in psoriasis reactions induced by anti-PD-1, at levels comparable with chronic psoriasis." (PMID 40936709, 2025). "The pathophysiology of psoriasis is complicated, involving an abnormal immune response with elevated cytokine levels like tumor necrosis factor alpha (TNF-alpha) and interleukin-6." (PMID 40370872, 2025). "In the case of psoriasis, for instance, related inflammatory cytokines (e.g., TNF-α and IL-6) can reach the skin and trigger an inflammatory response." (PMID 39967732, 2025). "Infusion of mouse mesenchymal stromal cells that secrete IL-6 and TGF-β has been illustrated to accelerate the resolution of psoriasis-like skin inflammation, marked by epidermal thinning and reduced CD3+ T cell infiltration." (PMID 40303401, 2025). "In this cross-sectionalstudy, 60 psoriasis patients and 30 healthy controls were evaluated; PASI scores were recorded and serum TNF-α, IL-6 and IL-17levels was measured using ELISA." (PMID 41393395, 2025). "Here, we demonstrate that in psoriasis, HKGs such as STAT3, PPIF, and EIF5A are co‐opted by the IL‐17/IL‐6 signaling axis to drive keratinocyte activation." (PMID 40959079, 2025). "Shared inflammatory mechanisms, particularly elevations in pro-inflammatory cytokines such as IL-6, TNF-α, and IL-17, underpin the connection between psoriasis and psychiatric disorders." (PMID 40428224, 2025). "On the contrary, treatment with methylene chloride fraction of A. chinensis stalk succeeded to mitigate inflammatory response via reducing IL-1β, IL-6, IL-23, and IL-17 levels by 40, 34, 44, and 51%, respectively, relative to IMQ-induced psoriasis group." (PMID 40072672, 2025). "For example, sustained GOS intake for 10 weeks significantly reduced pro-inflammatory cytokines IL-1, IL-6, and TNF-α while increasing anti-inflammatory IL-10, leading to improved inflammatory symptoms of psoriasis." (PMID 41425939, 2025). "The formation of initial non-calcifying atherosclerotic plaque and endothelial inflammation has been observed, with the involvement of IL-6, IL-17 and TNF-α, whose levels are elevated in psoriasis, being postulated." (PMID 40584532, 2025). "SCFAs inhibit the NF–κB pathway and reduce the production of pro-inflammatory cytokines such as IL-1β, IL-6, and TNF-α, which can alleviate skin symptoms in psoriasis, acne, or HS." (PMID 41178942, 2025).
psoriasis (continued). "Total RNA was extracted and analyzed using qRT-PCR to assess the expression levels of psoriasis-related keratinocytes marker genes (KRT6, KRT16) and CD-related inflammatory cytokines (IL6, IL8, TNF-α)." (PMID 40406126, 2025). "Primary outcomes were Psoriasis Area and Severity Index (PASI), Dermatology Life Quality Index (DLQI), physician global assessment (PGA), interleukins (IL-6, IL-17, IL-23, IL-22), and adverse events." (PMID 41459063, 2025). "Through these receptors, estrogen can downregulate the production of pro-inflammatory cytokines, such as tumor necrosis factor-alpha (TNF-α), interleukin-6 (IL-6), and interferon-gamma (IFN-γ), all of which are central to the pathogenesis of psoriasis." (PMID 39860587, 2025). "No appreciable evidence was found on HaCaT hyperproliferation, as often reported in the literature, but we showed substantial differences between specific genes involved in the inflammation pattern related to psoriasis such as TLR-4, IL-6 and IL-23." (PMID 39941078, 2025). "In turn, hBD-2 in patients with psoriasis or RA increases the production of TNF-α, IFN-γ, IL-10, IL-1β, IL-6, and IL-22." (PMID 40062148, 2025). "Regarding psoriasis, PPS reduced pro-inflammatory cytokines (IL-6, IL-1β) in both psoriatic keratinocytes and a co-culture model mimicking the skin-adipose tissue interface." (PMID 41226468, 2025). "Psoriasis is characterized by an exaggerated immune response, with proinflammatory cytokines such as TNF-α, IL-1, and IL-6 contributing to disease pathogenesis through sustained inflammation." (PMID 40678620, 2025). "Megamonas was significantly elevated in psoriasis patients, correlating with pro-inflammatory cytokines (TNF-α, IL-6)." (PMID 40333159, 2025). "ASO-210-loaded UCMSC-exosomes reduced psoriasis symptoms, exhausted Th17 cells and reduced enrichment of proinflammatory cytokines, such as IL-17A, IFN-γ, IL-6 and TNF-α, in both spleen and skin lesions in vivo." (PMID 39861699, 2025). "In addition, IL-17 can also promote the production of IL-6, which can not only activate and attract more inflammatory cells to the damaged area but also lead to abnormal skin desquamation and hyperkeratosis, which further promotes the formation and development of psoriasis plaques." (PMID 40430037, 2025). "Our cytokine analysis showed elevated levels of IL-6, IL-18, and IL-33, demonstrating a complex network of interactions in TNF inhibitor-induced psoriasis." (PMID 40678000, 2025). "This cascade activates epidermal keratinocytes to release pro-inflammatory cytokines, such as IL-1, IL-6, CXCL1, and CCL20, exacerbating the onset and progression of psoriasis symptoms." (PMID 39338338, 2024). "In general, proinflammatory cytokines and factors stimulating proliferation in psoriasis are produced mainly by T cells (IL-17, IL-21, IL-22, IFN-γ), DCs (TNF-α, IL-6, IL-20, IL-23, NO), and KCs (antimicrobial peptides (AMPs), IL-20, chemokines)." (PMID 38642273, 2024). "Recent studies have suggested that CBD’s effects on skin diseases such as allergic contact dermatitis, acne, and psoriasis are attributed to the inhibition of pro-inflammatory cytokines such as TNF-α, IL-1β, IL-6, and IL-17A." (PMID 39335596, 2024). "The results showed that the IL-17A, IL-6, IL-23, and TNF-α levels increased significantly in IMQ-induced mice with psoriasis." (PMID 39062965, 2024). "Thus, targeting IL-6 could be effective in treating psoriasis." (PMID 39590306, 2024). "In vivo studies showed that isozoranthin reduced TNF-α, IL-6, IL-23, and IL-17 levels in the sera of mice, effectively alleviating IMQ-induced psoriasis in mice." (PMID 39338338, 2024).
psoriasis (continued). "IL-6 was found to activate the STAT3 and Th17 pathways in psoriasis, promoting inflammation and keratinocyte proliferation." (PMID 39590306, 2024). "CCL20, IL-6, IL-20, IL-17C, and PI3 were previously found to be elevated in patients with psoriasis." (PMID 39224116, 2024). "Network pharmacology revealed 259 active components targeting pathways in psoriasis, focusing on TNF, IL-6, and IL-1β." (PMID 38425649, 2024). "APS improved psoriasis-like dermatitis in mice by inhibiting skin macrophage infiltration and reducing serum levels of TNF-α, IL-1β and IL-6." (PMID 39338338, 2024). "Research has shown that sleep deprivation increases pro-inflammatory cytokines such as IL-6 and TNF-α in psoriasis." (PMID 39411067, 2024). "Patients suffering from both psoriasis and CVD have increased serum levels of Th17-dependent cytokines IL-6, IL-21, IL-22 and TNF." (PMID 39200092, 2024). "The correlation between IL-6 and TNF-α, and the development of psoriasis has been widely recognized." (PMID 39777115, 2024). "Results indicated that IDG and DXM significantly inhibited the expression of IL-6, IL-17A, MCP-1, and TNF-α in psoriasis-like lesions, with all findings reaching statistical significance, while the effect on IL-13 was not statistically significant." (PMID 39465158, 2024). "In patients with psoriasis, there is an imbalance between the levels of pro- and anti-inflammatory adipokines (TNF-α, IL-6, leptin, resistin, and vifastin which increases, and adiponectin which decreases)." (PMID 38473907, 2024). "In psoriasis patients, peripheral dysfunctional Treg cells demonstrate phosphorylation and the aberrant activation of STAT3 in response to the activities of IL-6, IL-21, and IL-23." (PMID 39684717, 2024). "This signaling program resembles wound healing and psoriasis, and these pathways are well-described as oncogenic in specific contexts, predominantly c-JUN, IL6/JAK/STAT3, and TGFβ." (PMID 39358322, 2024). "In various clinical trials, probiotics have been shown to significantly improve the severity of skin lesions and quality of life in psoriasis patients, and reduce levels of inflammatory markers such as high-sensitivity C-reactive protein(hs-CRP) and IL-6." (PMID 39170985, 2024). "A number of serum analytes identified by Olink analysis, including PI3, IL-17C, CCL20, IL-20, IL-6, CXCL9, and CXCL10, have been previously identified as being elevated in serum samples of patients with psoriasis." (PMID 39224116, 2024). "Another study identifies that patients with NAFLD and psoriasis have elevated CRP and IL-6 values, but low adiponectin values." (PMID 38473907, 2024). "We also found that IL-6 and TNF-α are aberrantly expressed in psoriasis reactions induced by anti-PD-1, at levels comparable with chronic psoriasis." (PMID 38495872, 2024). "Studies show that cytokines, such as IL-6, that rely on JAK for their signal transduction are major contributors to chronic inflammation in psoriasis and atopic dermatitis." (PMID 38256910, 2024). "The role of HSP72 in psoriasis needs more elucidation as, in one study where systemic inflammation was induced by LPS, HSP72 induced by thermal pre-treatment inhibited IL-6 and TNF-α." (PMID 38666958, 2024). "Psoriasis-like erythematous appearance and microscopic features were significantly reduced, along with a notable decrease in the tissue gene expression of core psoriasis cytokines, such as IL-23, IL-17A, IL-22, TNF-α, and IL-6, after the capsaicin treatment." (PMID 39338338, 2024). "Inflammation-related factors, such as inducible nitric oxide synthase (iNOS), cyclooxygenase (COX)-2, IL-1, IL-6, and neutrophil proliferation, are downregulated by PF-EO treatment in the full skin and epidermis of an IMQ-induced psoriasis in mouse." (PMID 38791435, 2024). "Other biologics include IL-6 inhibitors, T-cell co-stimulation blockers, and CD20 antibodies used for RA, IL-17 and IL-23 inhibitors for psoriasis and PsA, and IL-12/-23 inhibitors used for psoriasis, PsA and IBD." (PMID 38891983, 2024).
psoriasis (continued). "In this study, TAN significantly inhibited the levels of iNOS, TNFα, IL-6, IL-10, IL-20, MIF, and MCP-1 in psoriasis mice, which had a wide range of inflammatory inhibitory effects." (PMID 38832986, 2024). "Current evidence suggests that IL-23, IL-6, and TNF-α play pivotal roles in the pathogenesis of psoriasis." (PMID 37275851, 2023). "The common occurrence of psoriasis on the skin primarily involves an inflammatory response involving IFN-α, IFN-γ, IL-1, IL-6, IL-17, IL-22, and IL-23 from dendritic cells, macrophages, and helper T cells (Th cells)." (PMID 37629529, 2023). "Pro-inflammatory cytokines and chemokines, including IL-6, IL-8, and TNF-α, play a critical role in the initiation and progression of many chronic inflammatory skin diseases, such as psoriasis or atopic dermatitis." (PMID 36979014, 2023). "In mice with psoriasis, L. pentosus GMNL-77 (2 × 109 CFU/day) down-regulated the mRNA level of IL-6, which improved psoriasis symptoms." (PMID 37111171, 2023). "The cytokines driven by NF-κB activation in psoriasis, including IL-17, TNF-α, IL-1β, and IL-6, were increased by IMQ exposure (p < 0.05)." (PMID 37111171, 2023). "Through intragastric administration, CUR can alleviate psoriasis‐like lesions of mice by decreasing PASI scores, reducing the level of IL‐6, IL‐17A, IL‐22, IL‐23, TNF‐α, and TGF‐β1, promoting the expression of IL‐10." (PMID 37647442, 2023). "In this study, the concentrations of IL-6, IFN-γ, and TNF-α were significantly elevated in the psoriasis group compared with the healthy group." (PMID 37596509, 2023). "IL-6, TNF-α, IL-23, and IL-17 levels significantly increased in IMQ-induced mice with psoriasis (p < 0.01)." (PMID 36992832, 2023). "Upon activation of the mTOR network, diverse cytokines and other pro-inflammatory mediators, such as IL-6, CXCL8, and IL-22, are released, which increases the inflammation and proliferation of cells commonly seen in psoriasis." (PMID 37371141, 2023). "The high expression of LMO4 was consistent with high levels of IL‐6, p‐AKT, and p‐STAT3 in the lesions of both psoriasis patients and imiquimod‐induced psoriasis‐like mice." (PMID 38156380, 2023). "Resistin was shown to correlate with the severity of psoriasis and to enhance the production of tumor necrosis factor-α (TNF- α) and interleukin-6 (IL-6), both of them being part of the pathogenesis of psoriasis." (PMID 37895330, 2023). "Using HaCaT cells, it was shown that metformin inhibits the expression of inflammatory cytokines (IL-6 and TNF-α) and downregulates the growth factor VEGF thus inhibiting the inflammatory response in psoriasis by inhibiting mTOR." (PMID 37371141, 2023). "Peripheral blood mononuclear cells in patients with psoriasis produce S100A7 which increases the production of inflammatory cytokines such as IL-1β, IL-6, IL-8, and TNF-β." (PMID 37891988, 2023). "SIRT3 deficiency exacerbated the TLR7/8-XBP1s response via deacetylation activity targeting XBP1s, contributing to the transcription of proinflammatory cytokines IL-23, IL-6, and TNF-α and thus promoting psoriasis progression and disease severity." (PMID 37275851, 2023). "The whole blood GLUT 1 expression significantly increased in psoriatic patients and correlated positively with serum IL-6, fetuin-A, PTX3 levels and with the severity of psoriasis while negatively with serum PEDF levels." (PMID 38052851, 2023). "Attractively, the FeN4O2-SACs treatment has largely weakened the M5-stimulated psoriasis-like morbidity status and shows inhibited cell proliferation and reduced TNF-α, IL-6, and IL-8 mRNA expressions." (PMID 37880231, 2023). "Other proinflammatory cytokines contributing to inflammatory aggravation in psoriasis released by mast cells are TNF- α and IL-6." (PMID 37958980, 2023). "Here, the transcriptional levels of IL-6, IL-23p19, and CXCL-3 were elevated in the psoriasis-like mouse model, and this effect was reduced more in the GC group." (PMID 38139164, 2023).
psoriasis (continued). "IL-1β, which is secreted by macrophages and has a vital role in psoriasis immunity, and IL-6, which activates the JAK-STAT pathway and exhibits elevated levels in psoriasis patients’ lesions, were both significantly increased in psoriasis-induced mice." (PMID 38007430, 2023). "At baseline, serum levels of effector cytokines (IFN-γ, IL-17 and IL-22) and proinflammatory cytokines (IL-6, TNF-α) were higher in psoriasis patients relative to healthy controls." (PMID 37681925, 2023). "Activated immune cells release several cytokines, such as IL-23, IL-17, IL-20, IL-22, IL-1β, IL-6, and INF-γ, which play a vital role in the pathogenesis of psoriasis." (PMID 36838711, 2023). "When exposed to multiple triggers such as IMQ, stressed keratinocytes produce inflammatory cytokines, including IL-1β, IL-6, and TNF-α, which contribute to dermal DC activation and the initiation of psoriasis." (PMID 37717073, 2023). "Within the psoriatic group (G2), the Psoriasis Area and Severity Index (PASI) scores correlated positively with whole-blood GLUT1 mRNA fold changes and serum levels of IL-6, fetuin-A, and PTX3, and negatively with serum PEDF levels." (PMID 38052851, 2023). "S100A15 alone has the potential to increase keratinocyte production of IL-6, indicating the importance of S100A15 in the exacerbation of inflammatory reactions in psoriasis." (PMID 37891988, 2023). "Psoriasis is an autoimmune inflammatory disease characterized by cytokines elevated, including TNF-α, IL-1β, IL-6, and IL-17A." (PMID 35860030, 2022). "In conclusion, we demonstrated that IRh improved IMQ-induced psoriasis-like dermatitis by decreasing TNF-α, IL-6, IL-17A, and nuclear NF-κB levels in the skin, and increasing malondialdehyde (MDA) levels in plasma." (PMID 36556472, 2022). "In the current study, the levels of IL-6, IP-10/CXCL10, MIP-3α/CCL20, and ICAM-1 were upregulated in M5-stimulated HaCaT cells (in vitro model of psoriasis)." (PMID 35209199, 2022). "The common occurrence of psoriasis on the skin primarily involves an inflammatory response involving IFN-α, IFN-γ, IL-1, IL-6, IL-17, IL-22, IL-23 from dendritic cells, macrophages, and helper T cell (Th cells)." (PMID 35566346, 2022). "Previous studies have shown that inflammatory adipocytokines such as IL-6 and TNF-α formed in visceral adipose tissue are key cytokines in the pathogenesis of psoriasis, so it is believed that psoriasis is related to obesity." (PMID 36119103, 2022). "A study showed an improvement in PASI and a reduced level of pro-inflammatory markers (IL-6 and high-sensitivity CRP (hsCRP)) after one month of therapy with rosuvastatin in patients with mild or moderate psoriasis." (PMID 35743091, 2022). "IL-6 is significantly elevated in psoriasis and serum IL-6 correlates with psoriasis area and severity index (PASI) scores in patients with psoriasis." (PMID 35812457, 2022). "For example, C/EBPδ has been shown to play a role in the pathogenesis of psoriasis and in acute inflammatory signaling by regulating COX-2, IL-6, and TLR4." (PMID 35543413, 2022). "Therefore, targeting IL-6 and IL-17 may be a promising strategy for the treatment of psoriasis." (PMID 35055377, 2022). "In this study, we found that the expression of M1 markers (CD68 and iNOS) was enhanced in psoriasis mice and the pro‐inflammatory cytokines levels (TNF‐α, IL‐6, IL‐12, and IL‐23) were increased." (PMID 36444619, 2022). "Upregulated inflammatory cytokines in the skin and peripheral blood of psoriasis patients, such as interferons, TNF-a, IL-1, IL-6 and IL-10, had an effect on erythropoiesis, leading to the enhanced RDW." (PMID 35213665, 2022). "In the pathogenesis of psoriasis, PRINS inhibits the expression of cellular inflammatory factors [e.g., interleukin (IL)-1α, IL-1β, IL-6, IL-8, and tumor necrosis factor-α) and thus affects inflammatory responses." (PMID 36187126, 2022).